CTCF (CCCTC-binding factor)
Diseases named in the same sentence as CTCF in open-access papers (continued):
Sharing a sentence is not in itself a finding about the gene and the disease.
cancer (continued). "CTCF and BORIS have not previously been found expressed together except in tumours, leading to the hypothesis that CTCF and BORIS have conflicting functions that cause cancer when allowed to overlap." (PMID 18769711, 2008). "This expression pattern underpins the hypothesis that BORIS is the key regulator establishing the male germline imprint of IGF2, that it acts antagonistically to CTCF and defines its inclusion within the cancer-testis group of genes." (PMID 18769711, 2008). "In cancer, this spatial genome architecture becomes profoundly disrupted through alterations in DNA regulatory elements, dysregulation of architectural proteins such as CCCTC-binding factor and cohesin, aberrant chromatin looping, and the breakdown or rewiring of topologically associating domains." (PMID 42249089, 2026). "Because differences in cancer stem cell frequencies exist between highly and low-tumorigenic BrCa cells, exploring whether O-GlcNAcylated CTCF regulates the 3D chromatin shape in the IL6 gene across BrCa cells with different stem cell proportions warrants further investigation." (PMID 40143084, 2025). "Conventional TF motif search methods are not feasible for this problem because the relative genomic location of the target oncogenic TF binding site relative to the cancer-specific CTCF site is unknown and can be very far, and it varies across different cancer-specific CTCF sites." (PMID 38397134, 2024). "Therefore, the direct binding of BORIS to intronic regions concurrently bound by CTCF in FER and GAL3ST1 genes appears to be associated with transforming these CTCF sites into active internal promoters, thereby driving alternative cancer-testis-specific transcriptional start sites." (PMID 38297316, 2024). "Finally, we identified putative pathogenic alterations in multiple cancer genes, including genes involved in epigenome editing and 3D genome organization, such as EP300, CTCF, and STAG2, which we validated by targeted sequencing of an independent cohort of 115 BM samples." (PMID 36561283, 2022). "CTCF function is essential for some and maybe all cancer cells." (PMID 35625988, 2022). "To further validate the specificity of CTCF binding sites proximal to HCC‐associated genes, we integrated the CTCF ChIP‐seq data from ENCODE and ascertained that these CTCF binding sites are indeed enriched as cell‐specific when compared to 29 ENCODE cancer cell lines and 70 non‐cancer cell lines." (PMID 36911294, 2022). "Fused CDs or neo‐CDs within the entire cell population might be masked to varying degrees if the chromosomes of heterogenous cancer cells do not undergo deletion or duplication of CTCF‐associated boundary insulators." (PMID 35570408, 2022). "Thus, we speculated that targeting CTCF-PD-L1 could overcome 5-FU resistance in GC by increasing cancer cell stemness and downstream signaling." (PMID 35572560, 2022). "Thus, failed Pc-dependent autorepression and/or defective repression of super-enhancers via CTCF could further elevate MYC to promote cancer progression." (PMID 32527935, 2020). "The existence of at least two cellular settings (male germ cells and cancer cells) in which CTCF and BORIS are co-expressed raises the question of whether they associate cooperatively or competitively with a finite number of recognition sequences in the genome." (PMID 29077515, 2018). "Thus, a CTCF-dependent enhancer-docking mechanism, which presumably facilitates interaction with different cell-specific enhancers during development, is exploited by cancer cells to dysregulate expression of prominent oncogenes." (PMID 29641996, 2018).
cancer (continued). "This could be due to integration of the virus such that the E2 coding sequence is disrupted, but in addition to this widely reported mechanism of HPV-driven carcinogenesis, it will be important to determine the mechanism and consequence of CTCF exclusion in cancers with integrated HPV DNA." (PMID 30359362, 2018). "Overall, this section demonstrates a number of CTCF mechanisms, by which its abundance, diversity in binding sites, and impact on epigenetic changes at the level of both histone modifications and DNA methylation, deserve consideration in pathways to epigenetic dysfunction and cancer." (PMID 28587163, 2017). "Thus, we evaluated the effects of CTCF knockdown on the proliferation of cancer cells." (PMID 28977939, 2017). "The question of how CTCF expression changes might affect cell phenotype has been more directly addressed in human embryonic kidney 293 cells, Hela cells and several other growth-transformed and cancer cell lines." (PMID 28587163, 2017). "Together, these studies suggest that reductions in the function or amount of CTCF leads strongly to epigenetic instability (at the level of both histone modifications and DNA methylation) in human cells and that the instabilities can precede and accelerate cancer progression in rodent cells." (PMID 28587163, 2017). "Therefore, CTCF deserves consideration in pathways to epigenetic dysfunction and cancer." (PMID 28587163, 2017). "Moreover, the viral perturbation of host cellular networks reflected disease etiology in that host genes (e.g. CTCF, RHOA, and CDKN1B) identified were frequently essential and significantly associated with Mendelian and orphan diseases, or somatic mutations in cancer." (PMID 27632082, 2016). "Their findings and our findings indicate that each BORIS isoprotein has a distinct gene regulatory network modulating different gene transcription or competing with another variant or CTCF and that BORIS variant B6 might be specifically related to gene expression of cancer stemness." (PMID 26849232, 2016). "Thus, these analyses showed that CTCF&BORIS co-regulation of corresponding genes is of critical importance for the transcriptional program of both germ and cancer cells, and represents a functionally distinct mode of transcription control compared with CTCF homodimer bound at the same regions." (PMID 26268681, 2015). "Increased CTCF expression in cancer cells could be anti-apoptotic or promote cell proliferation." (PMID 24393203, 2014). "Importantly, BORIS is abnormally activated in many different types of cancer, including gynecologic malignancies, and may compete with CTCF for binding sites in this context." (PMID 23745176, 2013). "Further, we showed that RICTOR regulates three transcription factors, like ZFX, CTCF, and ELF1, that can further regulate multiple genes/enzymes, including some from the sphingolipid and ganglioside pathways in a cell-type and cancer-context-dependent manner." (PMID 40934285, 2025). "To inspect the participation of CTCF in the transcriptional regulation of the IL6 gene, we downregulated CTCF mRNA expression by transitorily transfecting specific siRNAs against CTCF mRNA in both MCF7 and MDA-MB-231 cancer cells." (PMID 40143084, 2025). "The relationship between CTCF and IL6 has been evaluated in several biological scenarios distinct from cancer." (PMID 40143084, 2025). "Chromatin structural regulators, such as CCCTC-binding factor (CTCF) and Yin Yang 1 (YY1), have emerged as critical players in cancer biology." (PMID 40565099, 2025).
cancer (continued). "This review aims to provide a comprehensive analysis of the distinct amino acid sequences, the target sites, expressions patterns and functions of CTCF and CTCFL in normal tissues and cancers." (PMID 39430552, 2024). "We first compared CTCF and BORIS genome-wide binding profiles in cancer cells (K562) with the transcriptional programs executed during both spermatogenesis and carcinogenesis." (PMID 38297316, 2024). "Despite their distinct expression patterns, the cooperative and competitive mechanisms by which CTCF and CTCFL regulate target gene expression in spermatocytes and cancer cells remain inadequately understood." (PMID 39430552, 2024). "When CTCF and BORIS are co-expressed, essentially only in germline and cancer cells, they tend to form a heterodimer at clustered (double) CTCF binding sites, which encompass two or more CTCF binding consensus sequences (2xCTSes)." (PMID 38297316, 2024). "Here, we have characterized the transcriptional outcome of CTCF-BORIS heterodimerization in somatic normal and cancer cells." (PMID 38297316, 2024). "In cancers, CTCFL overexpression competes with CTCF for DNA binding, leading to aberrant gene expression, a more relaxed chromatin state, and altered chromatin loops." (PMID 39430552, 2024). "This review represents the first effort to systematically summarize how differential expression patterns of CTCF and CTCFL influence gene regulation and chromatin architecture across normal somatic cells, sperm and cancer cells." (PMID 39430552, 2024). "In this review, we comprehensively examine the literature on the divergent amino acid sequences, target sites, expression profiles and functions of CTCF and CTCFL in normal tissues and cancers." (PMID 39430552, 2024). "This explains the opposite consequences of their expression in cancer; while BORIS promotes cell proliferation and has been classified as an oncogene, CTCF is a known tumor suppressor." (PMID 37408191, 2023). "Upon abnormal expression in cancer cells, BORIS outcompetes CTCF from its binding sites introducing havoc into the gene expression program, mitosis, and even genome stability." (PMID 36983050, 2023). "Cancer growth can also be reliant on high expression of specific E2 cell cycle target genes including AURKA, KIF4A, STAG1, CTCF, and RPA1, all of which were identified highly expressed in at least one of the at-risk samples studied here." (PMID 35459280, 2022). "However, not all cancer-specific mutations in CTCF affect its binding." (PMID 36589746, 2022). "CTCF controls the metallothionein family's transcription activity in HCC, and editing CTCF binding sites provides a novel hint for cancer treatment." (PMID 34988109, 2021). "The top 5 important TFs observed in more than 10% of all cancer genomes include SP1, RXRA, NR2F2, GABPA, and CTCF." (PMID 33647036, 2021). "Multivariable analyses were performed in all cancers and the subset of ERG‐negative and ERG‐positive cancers evaluating the clinical relevance of CTCF expression in different scenarios." (PMID 31736271, 2020). "CTCFL (or CCCTC-binding factor or BORIS (brother of the regulator of imprinted sites)) regulates testis-specific expression in spermatogenesis and is known to be a cancer antigen." (PMID 33113971, 2020). "ABCG2 has been suggested to be involved in clinical multidrug resistance (MDR) in cancer, and we found that ABCG2 was activated by CTCF in CRC." (PMID 32688344, 2020). "In cancer cells where BORIS expression is aberrantly activated, BORIS-only sites were depleted of cohesin occupancy, while CTCF&BORIS sites were enriched with cohesin, indirectly suggesting that BORIS alone is not able to retain cohesin." (PMID 31937660, 2020). "A comparison of the overlap of methylated CTCF sites between breast and PCs in the TGCA reveals only 48 CG sites (2%) were common to both cancers of which 16 also contained CTCF sites." (PMID 32503656, 2020).
cancer (continued). "While healthy somatic tissues express only CTCF, CTCF and BORIS are normally co-expressed in meiotic and post-meiotic germ cells, and aberrant activation of BORIS occurs in tumors and some cancer cell lines." (PMID 29077515, 2018). "CTCF paralogue, CTCFL (CCCTC-binding factor-Like, also known as BORIS, Brother of the Regulator of Imprinted Sites or CT27: Cancer/Testis antigen 27) is transcribed from a gene in human chromosome 20q13.31 (Gene ID: 140690, Ensembl gene: ENSG00000124092)." (PMID 30275357, 2018). "Previous studies have reported that a variety of genes regulated by CTCF, including RB1, TERT and BAX, are involved in proliferation and apoptosis in cancer cells." (PMID 28977939, 2017). "Incidentally, even the most comprehensive genome-wide studies on CTCF tended to ignore the possible simultaneous presence of BORIS in cells studied, be it cancer or embryonic stem cells." (PMID 27588042, 2016). "Thus, developing a novel reovirus that targets CTCF transcription factor binding sites by partial inhibition of viral replication or partial oncolytic activity may provide a potential strategy for targeted cancer therapy." (PMID 27632082, 2016). "As a result of this study, by employing ChIP-chip and ChIP-seq approaches, we characterized CTCF and BORIS binding patterns of genomic repeat binding upon aberrant BORIS expression in the K562 cancer cell line, which is dependent on BORIS for proliferation." (PMID 27588042, 2016). "Taking into account the important role of CTCF in regulating TE expression and epigenetic maintenance, it is possible that the aberrant activation of its germline paralog CTCFL/BORIS in cancer has an impact on repeat physiology and genome stability." (PMID 27588042, 2016). "We report here, for the first time, CTCF and BORIS occupancy of chromatin in germ cells and in several cancer cell types." (PMID 26268681, 2015). "We demonstrate that IGF2 expression in IH is strongly related to the expression of a cancer testes and suspected oncogene BORIS (paralog of CTCF), placing IH in the unique category of being the first known benign BORIS positive tumor." (PMID 26496499, 2015). "The overlap between our set of data for CTCF and BORIS occupancy in cancers with the regions of histone retained in human sperm showed the specific enrichment of histones at 2xCTSes, but not at 1xCTSes." (PMID 26268681, 2015). "We further show that CTCF and BORIS bound regions (CTCF&BORIS) typically contain at least two proximal CTSes (2xCTS) in germ and cancer cells." (PMID 26268681, 2015). "The clustered CTCF binding sites constrain CTCF to form homodimers in normal somatic cells and heterodimers with BORIS in germ and cancer cells expressing BORIS." (PMID 26268681, 2015). "Our study provides the first comprehensive analysis of CTCF and BORIS occupancy in cancer and germ cells, where the two paralogous proteins are co-expressed." (PMID 26268681, 2015). "CTCF insulates and shields tumour suppressor genes, like Cdh1, p16 and RASSF1A, from being epigenetically silenced in cancers; on the other hand, when such DNA loci become methylated, CTCF gets repelled or is unable to bind anymore." (PMID 25492890, 2015). "Our analysis in cancer cell lines K562 and MCF7 further revealed that the majority of the cCTCF sites were located in the CTCF-mediated chromatin interactions from ChIA-PET." (PMID 23945083, 2013). "The pattern of BORIS isoform upregulation was similar in both cancer cell lines, suggesting a common mechanism of BORIS isoform repression by CTCF at least in some cancer cell lines." (PMID 21079786, 2010). "Future studies analyzing the occupancy of CTCF target sites by BORIS isoproteins and expression profiles of potential targets in germ cells and cancers will be needed to decipher the functions of BORIS isoproteins." (PMID 21079786, 2010).
cancer (continued). "In analyzing CTCF and BORIS expression in human testis, embryonic stem (ES) cells, and several cancer cell lines by RT-PCR, we were able to amplify the full-length ZF-encoding regions of both genes." (PMID 21079786, 2010). "We therefore conclude that while CTCF is expressed as a single transcript in human testis and cancers, BORIS is expressed as multiple isoforms in the testis, ES cells and in cancer cell lines, specifically in cells with increased DNA hypomethylation." (PMID 21079786, 2010). "Aberrant expression of BORIS in cancer cells likely results in a competition between BORIS and CTCF proteins for binding to CTCF DNA binding target sites (CTSes)." (PMID 21079786, 2010). "It has been suggested that the co-expression of CTCF and BORIS could be responsible for epigenetic deregulation leading to cancer." (PMID 39809819, 2025). "Through in vivo and ex vivo experiments, we demonstrated that CTCF promotes the transcription of Migration and Invasion Enhancer 1 (MIEN1), enhancing neutrophil migration toward cancer cells, and stimulates IL-1β secretion, leading to a malignant phenotype in CRC cells." (PMID 40959269, 2025). "CTCF depletion leads to the disruption of chromatin organization around the DNA damage sites, which abolishes the recruitment of essential DNA damage repair proteins BRCA2 and RAD51, as well as impairs homologous repair in the IDH mutant cancer cells." (PMID 39920158, 2025). "On the other hand, we did not observe any correlation between IL6 and CTCF expression levels in patients who underwent cancer recurrence (Figure A1(C))." (PMID 40143084, 2025). "Notably, among the 14 TFs whose binding sites were sex-dependently enriched across different cancers, eight were previously found to be enriched among sex-biased expressed genes, including SP1, ETV1, ELF1, E2F1, CREB1, CTCF, SIX2, and SOX2." (PMID 39716176, 2024). "The aberrant expression of CTCF and CTCFL might be responsible for the altered transcription of genes in cancer cells, potentially contributing to carcinogenesis." (PMID 39140283, 2024). "Recent studies have shown that CTCF and CTCFL are co-expressed at all stages of spermatogenesis and in certain cancer cells, suggesting their involvement in both the physiological process of male gametogenesis and tumorigenesis to modulate chromatin architecture." (PMID 39430552, 2024). "Targeting CTCF and TAD regulation may have broad applications in the treatment of cancer and other inherited diseases." (PMID 38658701, 2024). "We retrieved 2,134 essential genes in cancer development from DepMap20, and divided the CTCF sites looping to those genes into H3K27ac-negative (H3K27ac-) and H3K27ac-positive (H3K27ac+ ) groups." (PMID 36997534, 2023). "To demonstrate the effectiveness of these methods, we applied them to analyze CTCF’s binding sites identified from ChIP-seq, cancer-specific open-chromatin regions (OCRs) identified from ATAC-seq of 17 cancer types, and oligodendrocytes-specific OCRs identified from scATAC-seq." (PMID 37600846, 2023). "Similar to germ cells, depletion of CTCF and cohesin result in telomere damage in cancer cells, but unlike Smc1β−/− spermatocytes, TERRA levels are downregulated upon depletion of the cohesin component Rad21." (PMID 37636218, 2023). "Earlier studies had reported CTCF- and BORIS-binding sites in round spermatids and cancer cells." (PMID 34158481, 2021). "For example, we suppose that retinoid receptors, MAX and GATA3, as demonstrated in other types of cancer, could interact with the zinc finger protein YY1 that is known to modify chromatin structure and interact with insulators elements such as CTCF." (PMID 34449674, 2021). "Thus, by uncovering the vital roles of both CTCF and BORIS for the transcriptional program of normal spermatogenesis, we now can better understand the consequences of aberrant BORIS expression in cancers." (PMID 34158481, 2021).